MMP9 (matrix metallopeptidase 9)
Diseases named in the same sentence as MMP9 in open-access papers (continued):
Sharing a sentence is not in itself a finding about the gene and the disease.
Hyperglycemia (continued). "Additionally, hyperglycemia increased the activity of MMP-9." (PMID 34054705, 2021). "In addition, hyperglycemia has been shown to increase the expression of plasminogen activator inhibitor-1 and reduce plasma levels of MMP-9 in mice, and this effect may attenuate aortic aneurysm diameter." (PMID 34683112, 2021). "Moreover, hyperglycemia contributes to greater ICH by an increased stimulation of MMP-9 activity." (PMID 33925459, 2021). "However, it is unclear whether MMP9 is a mediator of hyperglycemia-induced stem cell death via apoptosis and pyroptosis." (PMID 32170070, 2020). "Thus, decreasing the levels of MMP9 may be a plausible strategy to mitigate hyperglycemia-induced apoptosis of hCSCs and it could be possibly applicable to other stem cells." (PMID 32170070, 2020). "Thus, MMP9 has a pivotal role in hyperglycemia-induced hCSCs death." (PMID 32170070, 2020). "Silencing of TET2 could prevent hyperglycemia-induced increase in 5hmC and MMP-9 transcription." (PMID 30987683, 2019). "Interestingly, there was synergism between hyperglycemia and HHcy for MMP-9 induction." (PMID 20828387, 2010). "As previously shown by our group, hyperglycemia decreases the expression of metalloproteinases, such as MMP2 and MMP9, which in the pancreas directly participate in the migration process of endocrine cell precursors through the degradation of ECM." (PMID 40563978, 2025). "Hyperglycemia promotes elevated local levels of IL-1β, TNF-α, and MMP-9, which not only exacerbate periodontal tissue destruction but also contribute to systemic insulin resistance and β-cell apoptosis." (PMID 40283677, 2025). "Hyperglycemia-induced inhibition of the deacetylase sirtuin 1 leads to AP-1 hyperacetylation and increased MMP-9 promoter binding, promoting MMP-9 expression." (PMID 40284474, 2025). "Hyperglycemia activates pro-inflammatory cytokines such as IL-6 and TNF-α, which in turn stimulate hepatic CRP production and upregulate MMP-9 expression at the site of tissue injury." (PMID 40364880, 2025). "We show that in the context of hyperglycemia, metformin reduced the secretion of EMMPRIN, MMP-9, and VEGF." (PMID 38672062, 2024). "All of these molecules were either downregulated or normalized in MMP9−/− hCSCs, demonstrating that MMP9 mediates hyperglycemia-induced apoptosis in hCSCs." (PMID 32170070, 2020). "Homocysteine supplementation exacerbated hyperglycaemia-induced MMP-9 and ROS levels and decreased Timp1 and its interactions with MMP-9." (PMID 32150828, 2020). "In conclusion, this study provides evidence that bioactive extracts from Korean red and white ginseng (GS-KG9 and GS-E3D) attenuate hyperglycemia and BBB disruption by inhibiting MMP-9 activation in STZ-induced diabetic rats." (PMID 32784852, 2020). "miR-21 contributes to renal fibrosis mediated by MMP-9/TIMP-1 and improves the glomerular lesions induced by TGF-β and hyperglycemia through the repression of proapoptotic signals, which inhibits the loss of podocytes." (PMID 33419373, 2020). "Hyperglycemia increases an expression and activity of MMP-2 and MMP-9 in aortic smooth muscle cells, vascular tissue, and plasma, affecting metabolism of the extracellular matrix." (PMID 28770228, 2017). "Studies suggest that hyperglycemia increases oxidative stress in various cells, leading to an activation of COX-2 which in turn induces a biosynthesis of MMP-2 and MMP-9." (PMID 28770228, 2017). "Instead, of external inhibition of STAT3, internal knockdown of STAT3 by siRNA also directly reversed the hyperglycemia-related high expression of CTGF, STAT3, and MMP9." (PMID 27519769, 2016). "The induction of MMP-9 in HHcy (CBS+/-) and hyperglycemia (Ins2+/-) due to oxidative stress is in line with the earlier findings." (PMID 20828387, 2010).
Hyperglycemia (continued). "In conclusion, PPAR-α stimulation prevented the decrease in claudins through a mechanism involving a correction of hyperglycemia, decreasing it in kidney oxidative stress and MMP-2 and MMP-9 activities, showing a promising nephroprotective action in the early stage of DN." (PMID 39684861, 2024). "Hyperglycemia promotes the production of proinflammatory cytokines TNF-α and IL-6 production, and the expression of these proinflammatory cytokines induces an increase in MMP9 expression in an autocrine and paracrine manner." (PMID 36820318, 2023). "Potential acute lowering of glucose does not fully mitigate downstream effects already initiated by hyperglycemia such as enhanced inflammation, endothelial cell dysfunction, neutrophil adhesion, MMP-9 activity, and ROS production." (PMID 34054705, 2021). "Suramin increases the urinary excretion of VEGF-A in normoglycemia and hyperglycaemia, possibly without the involvement of MMP-9." (PMID 33635529, 2021). "Our evaluation of mitochondrial function demonstrated that acute hyperglycemia or MMP9 ablation does not have significant effect on mitochondrial function in hCSCs." (PMID 32170070, 2020). "Inflammatory cytokines, such as tumor necrosis factor-alpha (TNF-alpha) and matrix metalloproteinase-9 (MMP-9) have been demonstrated to be involved in the pathogenesis of DED.Thirdly, hyperglycemia has also been confirmed to lead to histological alterations in the lacrimal gland." (PMID 29747621, 2018). "Results showed that the hyperglycemia-induced GAG alterations in the cell surface perlecan as well as in the ECM indeed upregulated the expressions of IL-6, IL-8, and MCP-1 and the activities of MMP-2 and MMP-9 and downregulated the expressions of TIMP-2." (PMID 23983782, 2013). "It should be noted that human placental tissue expresses Tie2 receptor and angiopoietins, with inflammatory mediators and hyperglycemia enhancing its release from the feto-placental endothelial cells and trophoblasts via induction of MMP2, MMP9 and MT1-MMP activities." (PMID 24376824, 2013). "Therefore, we determined the individual and combined effect of hyperglycemia and HHcy on MMP-2 and MMP-9." (PMID 20828387, 2010). "Finally, multiple recent studies confirm that NF-κB/AP-1 signaling directly controls MMP-9 transcription under inflammatory stimuli (e.g., TNF-α, hyperglycemia), providing a clear mechanistic approach through which reduced PON1 activity can propagate to MMP-9 overexpression and disease progression." (PMID 41304763, 2025). "In summary, the present study demonstrates that in type-1 diabetic kidney, hyperglycemia results in the downregulation of PPARγ and the upregulation of RXRα, RXRβ and RARγ1, which possibly contributes to elevated PAI-1 levels, and thus, elevated MMP-9 and MMP-13." (PMID 34680110, 2021). "We found that MMP9 is the key mediator of caspase-3 activation irrespective of hyperglycemia." (PMID 32170070, 2020). "We created MMP9−/− hCSCs to test the hypothesis that MMP9 mediates hyperglycemia-induced oxidative stress and cell death via apoptosis and pyroptosis in hCSCs, which is attenuated by the lack of MMP9." (PMID 32170070, 2020). "Similarly, MMP9 is required for the induction of pyroptosis in hCSCs and ablation of MMP9 blocks pyroptosis in hCSCs irrespective of hyperglycemia." (PMID 32170070, 2020). "In the case of MMP‐9, although it was found that serum level of MMP‐9 in patients with acute coronary syndrome with hyperglycaemia was significantly higher than those without hyperglycaemia, the source and the mechanism that explain this increase in diabetic patients were not identified." (PMID 29992758, 2018). "Hence, chronic hyperglycemia may exacerbate mitochondrial functions possibly through other deleterious factors, which include, at least in part, MMP-9, rather than via ROS production in the brain." (PMID 25133692, 2014).
Hyperglycemia (continued). "Plg levels were not affected by hyperglycaemia that, on the contrary, reduced plasmin activity by 1.3‐fold (P < 0.01) and increased MMP‐2/MMP‐9 levels and activity by 2.2‐, 2.4‐ and 2.2‐fold (P < 0.001)." (PMID 30426662, 2019). "Moreover, there was dramatic downregulation of caspase-3 activity in the NG group of MMP9−/− hCSCs versus hCSCs, which elicits that MMP9 could be important for initiation of apoptosis irrespective of hyperglycemia." (PMID 32170070, 2020).
periodontal disease (90 papers, 2008 to 2026). "In periodontal diseases, MMP-9 and IL-6 play roles in inflammatory-driven bone loss, while TNF-α and TRAP (ACP5) are implicated in osteoclast activation." (PMID 41559024, 2026). "The regimen reduced pathogenic bacteria, IL-1β, MMP1, and MMP-9, paralleling clinical reductions in periodontal disease." (PMID 41303313, 2025). "Collectively, the data support a reduction in host mediators (e.g., TLR-ATP, IL-1β, MMP-1, and MMP-9) with regimen treatment that are implicated in inflammation and periodontal disease destruction." (PMID 41303313, 2025). "The ratio of M1 to M2 macrophages correlates positively with the severity of periodontal diseases, which is associated with the expression of pro-inflammatory cytokines IL-1β and MMP-9 in gingival tissues." (PMID 40871666, 2025). "In parallel to our study, an excessive amount of MMP-9 production and activation were analyzed and linked to severe types of periodontal disease." (PMID 40281482, 2025). "MMP-8 and MMP-9 have been linked to periodontal disease in humans, according to a number of studies." (PMID 38535279, 2024). "Increased activity of the ECM remodeling proteins MMP2/MMP9 is often associated with periodontal disease, where this activity is coordinately regulated by gene expression and controlled enzymatic activity by a wide range of cytokines and growth factors." (PMID 37892119, 2023). "Elevated MMPs have been associated with increased inflammation and loss of tooth-supporting tissue present in periodontal disease, while periodontal treatment decreases inflammation and lowers MMP-9 levels." (PMID 33498206, 2021). "Neutrophils also produce various MMPs, such as MMP-9, which was detected at elevated levels in Il17ra−/− mice, and is associated with tissue destruction during periodontal disease and OM." (PMID 34220843, 2021). "As for MMP9 polymorphism, specifically MMP9-1562C>T, a meta-analysis published in 2016 related a reduced risk between the T allele and periodontal disease susceptibility in both Caucasian and Asian populations." (PMID 31065235, 2019). "Porphyromonas gingivalis lipopolysaccharide (Pg-LPS) circulates systemically in over 50% of periodontal disease (PD) patients and is associated with increased matrix metalloproteinase (MMP)-9." (PMID 24159380, 2013). "Several studies have shown a relationship between periodontal disease and genetic factors, including polymorphisms in interleukin (IL)-1, interferon-γ, IL-6, matrix metalloproteinase (MMP)-9, tissue inhibitor of MMP-2, vitamin D receptor, IL-1α, and IL-1β." (PMID 23050158, 2012). "MMP-8 and MMP-9 have been linked to human periodontal disease, according to numerous research." (PMID 38535833, 2024). "Overall, our results showed selective inhibition of IL-1β, TNF-α, IL-8, MMP-2, and MMP-9 associated with hesperidin, which could represent a promising novel approach to the treatment or prevention of periodontal disease." (PMID 37373533, 2023). "In periodontal diseases, models overexpressing IL-6 or TNF-α mimic inflammatory bone loss, while MMP-9 knockout mice display reduced periodontal degradation." (PMID 41559024, 2026). "Tetracyclines, particularly sub-antimicrobial dose doxycycline, provide one of the most direct and clinically validated means of MMP-9 inhibition, supported by trials in periodontal disease and vascular remodeling." (PMID 41304763, 2025). "Tetracycline derivatives, particularly sub-antimicrobial dose doxycycline, directly inhibit MMP-9 activity and are clinically validated in the treatment of periodontal disease and vascular remodeling." (PMID 41304763, 2025). "Both MMP-8 and MMP-9 levels in GCF have shown promise as diagnostic and prognostic markers for periodontal disease." (PMID 39275315, 2024). "In periodontal disease, MMPs (e.g., MMP-9) are highly secreted and degrade the extracellular matrix, whereas TIMPs levels can be significantly decreased." (PMID 39599607, 2024).
periodontal disease (continued). "Enzymes such as MMP-8 and MMP-9 play a significant role in the progression of periodontal disease by breaking down collagen in tissues and alveolar bone, leading to its degradation." (PMID 38744331, 2024). "MMP-9 is produced during the degradation of connective tissue in inflammatory conditions, such as periodontal disease, and is essential component of the osteoclast resorption process." (PMID 39548434, 2024). "Other studies have identified an association between periodontal disease and increased PGE2 and MMP-9 in GCF." (PMID 39275315, 2024). "MMP-9 has been shown to play a role in periodontal disease, a chronic inflammatory condition that affects the tissues surrounding and supporting the teeth." (PMID 38744331, 2024). "Matrix metalloproteinases, particularly MMP-8 and MMP-9, have gained significant attention as potential biomarkers for periodontal disease." (PMID 39275315, 2024). "Among them, the concentrations of MMP-8 and MMP-9 increased significantly in patients with periodontal disease and those with advanced periodontal disease, which can be used as potential markers for periodontitis screening and diagnosis." (PMID 36769328, 2023). "As matrix-metalloproteinases have been comprehensively investigated in the context of periodontal diseases, different studies are available highlighting the relevance of MMP-9 in periodontal inflammation." (PMID 37510279, 2023). "Because type I collagen is the major component of the periodontal extracellular matrix, special attention has been paid to the role of collagenases, especially MMP-8 and MMP-13 and gelatinases, MMP-2 and MMP-9, in periodontal diseases." (PMID 35163727, 2022). "MMP-9 levels are higher in chronic gingivitis but lower than in the presence of active periodontal disease." (PMID 35163727, 2022). "The authors identified that MMP-8, MMP-9, OPG, and IL-1β demonstrated a strong association with periodontal disease progression." (PMID 35626325, 2022). "For upregulated MMP9, it has been suggested that matrix metalloproteinases (MMPs) are key proteases involved in destructive periodontal diseases." (PMID 35571048, 2022). "On the other hand, MMP-2 and MMP-9 are mainly synthesized by neutrophils and macrophages and are involved in MMPs-mediated destructive periodontal disease." (PMID 35163727, 2022). "Genetic variations in the promoter region of the MMP-9 gene may have an effect on the transcription and synthesis of its proteins, which may influence the degradation of connective tissue of the protein and thus contribute to genetic susceptibility to periodontal disease." (PMID 35163727, 2022). "Matrix metalloproteinase (MMP)-1 and MMP-9 which played an important role in both diseases are upregulated in OLP patients with periodontal diseases." (PMID 36360666, 2022). "According to one study, AUC had the largest values for MMP-8, myeloperoxidase and MMP-9 in subjects with periodontal disease, the sensitivity to diagnosis being similar to the results obtained in the present study." (PMID 34829612, 2021). "The involvement of MMP-9 both in periodontal disease and in the orthodontic periodontal reshaping has already been demonstrated by several studies." (PMID 33498206, 2021). "Polyphenols and in particular, EPGCG, catechins, and also proanthocyanidins were shown to be particularly effective in downregulating MMP-9 expression induced by bacteria involved in the pathogenesis of periodontal disease, such as P. gingivalis." (PMID 34063147, 2021). "Various studies have shown that increased MMP-8 and MMP-9 levels characterize not only periodontal disease but also tend to increase during OTM." (PMID 33567492, 2021). "MMP-8, MMP-9, and MMP-13 have been demonstrated to be associated with the severity of periodontal disease and are promising candidate biomarkers in oral fluids such as gingival crevicular fluid (GCF), mouthrinse, and saliva." (PMID 30669541, 2019).